ATM (ATM serine/threonine kinase)
Diseases named in the same sentence as ATM in open-access papers (continued):
Sharing a sentence is not in itself a finding about the gene and the disease.
cancer (continued). "ATM and ATR are activated by oncogenic stresses, suggesting that cancer cells may rely on DNA damage response pathways to survive genomic instability." (PMID 37298208, 2023). "Hypersensitivity of ATM-defective cells to IR and the critical function of the ATR pathway for the survival of tumor cells has led to considerable interest in ATM and ATR as therapeutic targets for cancer therapy." (PMID 35406593, 2022). "Previous studies have offered some clues about the complexity of Atm mRNA translation but, despite the relevance of ATM in cancer and other diseases, not much is known." (PMID 36543128, 2022). "The other patient, who had a germline PV/LPV in RAD51C (detected also in the tumor) and in the ATM gene (not detected in tumor), had no family history of cancer." (PMID 35326583, 2022). "In addition, the cost of using WES to determine TMB is about 10 times that of using cancer hot spot panel sequencing to determine EGFR and ATM status." (PMID 35521981, 2022). "In addition, 2 of 70 patients with IPMN (2.8%) had cancer-related variations, and both were splice-site variations (RECQL4 c.2755 + 1G>A and ATM c.3576 + 1G>A)." (PMID 35171259, 2022). "Furthermore, CDK12-deficiency may promote proximal alternative last exon (ALE) splicing of certain DDR genes, such as ATM, thus limiting the abundance of full-length protein products, and in this way impeding DNA repair processes and further contributing to genome instability and cancer development." (PMID 35158934, 2022). "Moreover, in various cancer types, positive CTL score correlation with ATM protein, and neoantigens levels have been identified as being largely mutually exclusive." (PMID 36071479, 2022). "In our study, we report the co-occurrence of truncating mutations in ATM, CDK12, PTEN or ATR is present in 80% of MSS CRC with TMB-H and absent from TMB-L MSS cancers." (PMID 35740599, 2022). "ATM inhibition, ATR inhibition, Chk1 inhibition, PARP inhibition, and WEE1 inhibition have all been shown to lead to cGAS-STING pathway activation and potentiation of cancer immunotherapy." (PMID 36362142, 2022). "For example, inhibiting the activation of pathways between ATM and ATR could enhance the sensitivity of cancer cells to chemotherapeutics." (PMID 35303867, 2022). "A recent systematic review identified ATM, BRCA1, BRCA2, CDKN2A, CHEK2, and PALB2 as the most frequent genes harboring GPV in individuals with PDAC not meeting criteria for any cancer predisposition syndrome with varying degrees of family history." (PMID 35805029, 2022). "In this case, the ATM finding was related to the indication for testing (broad cancer phenotype) and did not technically meet the definition of an IF set forth in this report, or by the KidsCanSeq study, since it was sought after (cancer panel testing)." (PMID 36414972, 2022). "However, in primary cancer samples, ERBB2 mean increase to 8.1 with a decrease of ATM to 8.4 (p < 0.0001)." (PMID 36056635, 2022). "Thus, many cancer cells rely on DDR components, including ATM and ATR, to survive DNA-damaging events." (PMID 36207426, 2022). "Conversely, the exposure of ALT-positive cancer cells to TXT compounds failed to evoke the activation of both ATM- and ATR-dependent signaling cascade." (PMID 36437244, 2022). "We found that canagliflozin increased the activition of ATM/CHK2 in thyroid cencer cell, indicating DNA damage repair initiated, which may be related to insufficient energy in cancer cell." (PMID 35148777, 2022).
cancer (continued). "Numerous, promising preclinical and clinical studies suggest that ATM, ATR, CHK1, CHK2 and WEE1 inhibitors or modulators, alone or in combination with other therapeutics, could be potent therapeutic options for certain cancers, including TNBC." (PMID 36012478, 2022). "Kynurenic acid seems to be the hub in the metabolite/gene cancer correlation network inferred from CCLE, and several of the cancer genes significantly correlated with metabolites include pan-cancer actors such as MAX, ATM, PTEN, and BRAF." (PMID 35409231, 2022). "Two studies using whole-exome-sequencing and DNA sequencing targeting 287 cancer-related genes respectively, found that alterations in DNA repair genes may correlate with response to chemotherapy: ERCC2, ATM, RB1, and FANCC." (PMID 36322407, 2022). "Molecular aberrations that were shared in at least one P/X pair and that were previously recognized to have deleterious effects in human cancers included CHEK2 [K416E; 415S (SNP)], EGFR (158N), ATM (P1054R), STK11 (D194N), PIK3CA (E545K), KIT (798I; M541L), and RUNX1 (L56S)." (PMID 34714554, 2022). "Our findings substantially agree with the idea that Wee1 is rapidly recruited at DSBs in response to DNA damage via ATM-γH2AX-MDC1, driving Wee1 to recruit downstream HR repair proteins BRCA1 and RAD51 to DNA damage sites, as well as allowing cancer cells to escape damage and survive." (PMID 36575478, 2022). "Similarly, inhibition of other HRR genes, such as ATM and ATR, leads to BRCAness and sensitizes cancer cells to PARP inhibitors." (PMID 35328658, 2022). "Although their radiosensitizing capability was not as potent as that of the ATM inhibitor, our findings still justify their utilization in combination with IR to boost cancer killing." (PMID 35954456, 2022). "The patient without a family history of cancer had several germline mutations: a pathogenic PALB2 mutation, and a VUS in ATM, MLH1, CDK4 and BRCA1." (PMID 36359225, 2022). "Thus, the normal functions of ATM and BRCA1 are required for preventing malignant transformation, and defects in ATM and BRCA1 genes are observed in human cancers." (PMID 34068585, 2021). "A similar enrichment for signature 3 was found for PALB2 and RAD51C mutations or epigenetic silencing of the BRCA1 or RAD51C promoter, but not for inactivation of other cancer-associated genes, such as CHEK2 and ATM." (PMID 33670893, 2021). "Recent studies have shown that activation of ATM/ATR, besides regulating the cell cycle, could induce autophagy and help cancer cells survive; this makes them important targets for future anti-cancer therapies." (PMID 34575923, 2021). "Following large-scale cancer sequence analysis, many other HRD-related genes (CDK12, ATM, PALB2) were commonly found in mCRPC, and these non-BRCA DNA repair genes could be used as alternative biomarkers to predict the sensitivity of PARP inhibitors." (PMID 34975480, 2021). "In addition, recurrent breakpoints of SVs targeting cancer genes commonly occurred in frequently deleted regions, e.g., CDKN2A on 9p21.3, MAML2 and ATM on 11q21-22, RAD51B, and TRAF3 on 14q 24-32.3, CYLD and NLRC5 on 16q12.1-13." (PMID 34234122, 2021). "DDR genes including ATM, ATR, CHEK2, POLE, and POLQ could serve as potential biomarkers of ICI response, but their distinct and cancer-specific effects need to be investigated further." (PMID 34095878, 2021).
cancer (continued). "Thus, using targeted agents for DDR pathways, including inhibitors of ATR/CHK1, PARP, ATM, cyclin-dependent kinase 4/6 (CDK4/6), DNA-PK, WEE1, and aurora kinase B (AURKB) opens new exciting avenues for clinical development of ICB for cancer treatment." (PMID 34930377, 2021). "Hence, it is important to investigate the effects of PLK1, ATM and ALDOA on the DDR and the potential value of these proteins as targets in cancer therapy." (PMID 34565365, 2021). "ATM and its downstream molecule Chk2 are the primary kinases responsible for G1/S phase arrest of the cell cycle, and S-phase-specific DNA damage has been reported to activate the immune response including induction of CXCL9, -10 expression in cancer cells." (PMID 34413454, 2021). "A homozygous pathogenic variant in NBN was recently reported in an isolated POI case; however, no heterozygous NBN and ATM variants were reported as POI cause, although they have been associated with cancer predisposition." (PMID 33095795, 2020). "Such conversions may be dependent on a specific molecular context in the concerned cancers, for instance regarding EZH2 this could be either a concomitant overexpression of ATM or changing features in the interplay with Rev729,44." (PMID 33230143, 2020). "Based on the fact that DCZ3301 was an anti-cancer agent that induced DNA damage and the M phase cell cycle arrest, we speculated that DCZ3301 might also activate the ATM-ATR/CHK1 signaling pathway." (PMID 32517809, 2020). "We further evaluated whether USP52 phosphorylation by ATM affects CHK1 and RPA2 phosphorylation and render cells resistant to cancer therapy." (PMID 33097710, 2020). "Taken together, these studies strongly suggest that ATM inhibition may be a promising strategy to suppress CSC properties and improve cancer treatment outcomes." (PMID 32566127, 2020). "While we found several cancer signaling pathways enriched in PRMT5 inhibited cells, we also observed a depletion of pathways involved in various DNA repair pathways, such as BRCA1, nucleotide excision repair (NER) and ATM signaling." (PMID 32555249, 2020). "Similar to our observations pharmacologic inhibition of ATM with KU-55933 resulted in increased glucose derived lactate production while reduced mitochondrial respiration and accumulation of TCA cycle substrates occurred in MCF-7 cancer cells." (PMID 33273545, 2020). "HITT may represent an important brake in controlling the ATM-mediated DDR network, which is a key cell fate determinant, particularly upon prolonged exposure to DNA-damaging agents in cancer treatment." (PMID 32203529, 2020). "Moreover, the pathways of central carbon metabolism in cancer and cell cycle related to miR-654-3p and the target genes of PTEN and ATM were found to be different between QXXY patients and GYPXXY patients." (PMID 33178319, 2020). "We highlight our recent findings that PARP inhibition alone is cytostatic but not cytotoxic in ATM-deficient cancer cells and that the combination of a PARP inhibitor with an ATR (ATM, Rad3-related) inhibitor is required to induce cell death." (PMID 32183301, 2020). "Although there are currently no FDA-approved ATM inhibitors, many are being assessed as cancer therapeutics in clinical trials." (PMID 33120910, 2020). "Cancer cells are characterized by genome instability and defective DDR pathways and are often over‐reliant on the remaining intact part of the DDR network such as ATM and Chk1." (PMID 30886052, 2019). "By contrast, in cells with moderate radiosensitivity, over-expressed ATM substrates may delay the RIANS, thereby favoring cancer proneness and aging." (PMID 31717816, 2019).
cancer (continued). "Furthermore, the MRE11-RAD50-NBS1 (MRN) complex involved in the recruitment of ATM to sites of DNA double-strand breaks, and increased expression of MRN complexes have been observed in cancer cells." (PMID 31783569, 2019). "This indicates conservation of the suppression mechanism in a human cancer cell line and that it not only operates when ATM protein is absent, but also when its catalytic activity is inhibited." (PMID 30622252, 2019). "In our research, up-regulation of p-ATM/p-CHK2, p-ATR/p-CHK1 and CycB/CDK1 by EBV-miR-BART8-3p in NPC may, at least partly, explain the high radioresistance of this deadly cancer." (PMID 31471531, 2019). "In addition, we also examined the effect of RMP on the expressions of p-ATM, p-p65 and Bcl-xl in HCC tissues and paired normal hepatic tissues (adjacent to carcinoma from the same patient)." (PMID 31754340, 2019). "Finally, a recent work suggested that ATM regulates autophagy also by sustaining the levels and activity of ATG4C protease in cancer cells grown as mammospheres, characterized by low ROS levels." (PMID 29616191, 2018). "Identification of ATM substrates and/or CtIP effectors that are vital to DNA DSB repair in cancer cells but are dispensable to repair in normal cells could provide essential tools to combat treatment resistance." (PMID 30297868, 2018). "Cancer lineages that were predominately M-class tumors showed primarily neoantigen-dependent CTL scores, whereas lineages that were predominately for C-class tumors showed dependence on ATM." (PMID 29615613, 2018). "Next generation sequencing analysis with “Comprehensive Cancer Panel” highlighted the presence of multiple non-targetable mutations in the FLT4, UBR5, ATM, TAF1, and GUCY1A2 genes." (PMID 30172261, 2018). "Five of the pan-cancer ALFRED genes (BRCA1, ATM, BRCA2, NSD1, and TPCN2) were individually significantly enriched for RDGVs in cases versus controls (P < 0.05 by pan-cancer case-control analysis) with one additional gene, NIPAL3, marginally significant (P = 0.07 by case-control analysis)." (PMID 29973584, 2018). "The importance of ATM in supporting invasive tumor cell growth was also shown in MCF7, HT29, and HCT116 cancer cells." (PMID 28337983, 2017). "As a novel ATM inhibitor with highly selective radiosensitizing activity, GSK635416A holds promise as a lead in the development of drugs active in potentiating radiotherapy for HNSCC and other cancer types." (PMID 29088757, 2017). "Subsequently, other studies clarified that PARP1 is more active in cancer cells that, due to the lack of function of ATM, accumulated DNA damage (most represented and studied in prostate cancer, breast cancer, mantle cell lymphoma)." (PMID 28055979, 2017). "Using next generation sequencing for the 48 TruSeq cancer panel, we identified oncogenic mutations in FGFR2 and ATM genes in the ACC11 cell culture that had not been reported for this tumor." (PMID 28900283, 2017). "In particular, cancer cells with the inactive form of the ATM enzyme accumulated more DNA damage than cells that lacked the enzyme completely." (PMID 27304073, 2016). "As such, while missense ATM mutations in the kinase domain are not compatible with embryonic development when homozygous and are not found in A-T, they could predispose carriers to cancers, and maybe have more potent oncogenic potential than A-T causing truncating mutations." (PMID 27304073, 2016).
cancer (continued). "Irradiation (e.g. radiation therapy for cancers) and radiomimetic compounds (e.g. those used in cancer chemotherapy protocols) induce DSBs and other DNA lesions whose repair is severely impaired when ATM is absent." (PMID 27884168, 2016). "We previously showed that ATM protein expression level in malignant tumors independently predicts DSOS in early stage hormone negative breast cancer." (PMID 27741524, 2016). "Given that LDR can induce low levels of DSBs and ROS production, we hypothesized that it can activate ATM and its downstream effectors, which may account for the different biological effects of LDR in normal vs. cancer cells." (PMID 27708248, 2016). "This role of ATM at the replication fork explains the increased genomic instability, especially chromatid breaks, and hypersensitivity to CPT in murine cells as well as human cancer cells that express catalytically inactive ATM protein." (PMID 27304073, 2016). "Based on the data, we propose a non-canonical role for ATM in supporting pro-tumorigenic behavior of cancer cells." (PMID 26030852, 2015). "As dysfunction in the MRN functionality leads to hypersensitivity to DNA-damage agents by impairment of ATM pathway, inhibiting one of the MRN complex components represents an attractive strategy to induce cancer cell death in combination with DNA-damaging treatment." (PMID 26610585, 2015). "Chk1 mRNA expression was higher in MYC-Neuroblastoma-related (MYCN) amplified cancers and Chk1 was found to be phosphorylated on the auto-phosphorylation site Ser296 and the ATM activation site Ser345 in the absence of exogenous DNA damage insults." (PMID 24913641, 2014). "Moreover, recent evidence from our group has highlighted the functional significance of a cross-talk among ARF and ATM and how ARF can act as an “auxiliary” tumor suppressive mechanism throughout cancer progression in case the DDR pathway is compromised." (PMID 25101116, 2014). "In particular a positive role of ATM inhibition has been described in combined approaches with MET inhibitors and ATM inhibition suppresses cell proliferation and induces apoptosis in cancer cells with overactivated AKT." (PMID 24681585, 2014). "Moreover, components of the DDR are potential drug targets for reduction of cancer cell viability and small molecule inhibitors that target the activity of different DDR members, such as PARP, DNA-PK, and ATM, are currently under development." (PMID 25238049, 2014). "Sesquiterpene lactones compounds derived from Artemisia douglasiana promote accumulation of DNA damage markers such as phosphorylated form of ATM and focal organization of γH2AX and 53BP1, therefore, triggering cell cycle arrest and apoptosis in HeLa, S3, MCF-7 and WI-38 cancer cells." (PMID 25002129, 2014). "Materials and Methods: DNA was isolated from blood samples collected from 100 AI and 100 non-AI cancer patients undergoing radiation therapy, and a blinded assessment of the ATM sequence was conducted." (PMID 24416720, 2013). "The ATM gene has not been studied in Northern Plains AIs, a population that exhibits disproportionate burden of cancer mortality." (PMID 24416720, 2013). "We demonstrate that the ATM gene and the PAPPA2 gene could be identified as cancer prognosis related genes." (PMID 24069199, 2013). "Moreover, there is evidence suggesting that ATM and PI3K (activators of NFAT5) are activated during hypoxia in cancer cells." (PMID 22768306, 2012). "We and others suggest that in several cancer contexts, among which HCC, ATM expression and status might play a role in the efficacy of chemotherapy agents that trigger DNA damage as ehancers of TRAIL sensitivity." (PMID 24213315, 2012).